COL4A2 (collagen type IV alpha 2 chain)
Description:
Type IV collagen is the major structural component of glomerular basement membranes (GBM), forming a 'chicken-wire' meshwork together with laminins, proteoglycans and entactin/nidogen. Canstatin, a cleavage product corresponding to the collagen alpha 2(IV) NC1 domain, possesses both anti-angiogenic and anti-tumor cell activity. It inhibits proliferation and migration of endothelial cells, reduces mitochondrial membrane potential, and induces apoptosis. Specifically induces Fas-dependent apoptosis and activates procaspase-8 and -9 activity. Ligand for alphavbeta3 and alphavbeta5 integrins.
Synonyms: FLJ22259; DKFZp686I14213; BSVD2; BSVD2A; BSVD2B; ICH; POREN2
Tractability: Antibody: its Gene Ontology location is reachable by antibodies, with high confidence; UniProt places it where antibodies can reach, with medium confidence; UniProt predicts a signal peptide or a membrane-spanning region. PROTAC: its protein half-life has been measured. Other modalities: an approved drug acts on it.
Gene: Protein-coding gene on chromosome 13 (110,305,812 to 110,513,209, forward strand). Ensembl gene ENSG00000134871.
Subcellular location: Secreted, extracellular space, extracellular matrix, basement membrane
Subcellular location (Human Protein Atlas): Vesicles; Predicted to be secreted
Pathways (Reactome):
Extracellular matrix organization: Anchoring fibril formation; Assembly of collagen fibrils and other multimeric structures; Collagen biosynthesis and modifying enzymes; Collagen chain trimerization; Collagen degradation; Crosslinking of collagen fibrils; ECM proteoglycans; Fibronectin matrix formation; Integrin cell surface interactions; Laminin interactions; Non-integrin membrane-ECM interactions
Developmental Biology: NCAM1 interactions
Disease: Attachment of bacteria to epithelial cells
Signal Transduction: Signaling by PDGF
Vesicle-mediated transport: Scavenging by Class A Receptors
Gene Ontology:
Molecular function: extracellular matrix structural constituent conferring tensile strength; molecular adaptor activity; protein binding; extracellular matrix structural constituent
Biological process: endodermal cell differentiation; negative regulation of angiogenesis; collagen fibril organization; collagen-activated tyrosine kinase receptor signaling pathway; extracellular matrix organization; cellular response to transforming growth factor beta stimulus; DNA-templated transcription; response to activity
Cellular component: collagen type IV trimer; extracellular exosome; extracellular matrix; endoplasmic reticulum lumen; extracellular region; basement membrane; collagen trimer
Genetic constraint (gnomAD): Loss-of-function variants: 95 observed, 182.34 expected, observed/expected ratio (o/e) 0.52, 90% interval 0.44 to 0.62. The upper end of that interval is the gene's LOEUF score, 0.62, which puts it in group 2 of 6, group 1 being the genes least tolerant of losing a copy. Missense variants: 1,925 observed, 2,236.7 expected, observed/expected ratio (o/e) 0.86, 90% interval 0.83 to 0.89. Synonymous variants: 877 observed, 871.6 expected, observed/expected ratio (o/e) 1.01, 90% interval 0.95 to 1.06.
Homologues: Orthologues: chimpanzee COL4A2 (99% identical), macaque COL4A2 (96% identical), dog COL4A2 (87% identical), pig COL4A2 (85% identical), rat Col4a2 (84% identical), mouse Col4a2 (84% identical), rabbit COL4A2 (70% identical), guinea pig COL4A2 (59% identical), tropical clawed frog col4a2 (58% identical), zebrafish col4a2 (52% identical). Paralogues in human: COL4A6 (52% identical), COL4A5 (47% identical), COL4A1 (46% identical), COL4A3 (44% identical), COL4A4 (40% identical), COL7A1 (35% identical), COL5A1 (33% identical), COL11A1 (32% identical), COL11A2 (32% identical), COL5A3 (31% identical), COL2A1 (30% identical), COL1A1 (30% identical), and 25 more.
Diseases named in the same sentence as COL4A2 in open-access papers:
COL4A2 is named in the same sentence as 186 diseases in open-access papers, as found by Europe PMC text mining. Sharing a sentence is not in itself a finding about the gene and the disease. The quoted sentences say what the papers report.
Stroke (18 papers, 2012 to 2025). Sudden impairment of blood flow to a part of the brain due to occlusion or rupture of an artery to the brain. "Individuals with pathogenic variants in COL4A1 and COL4A2 had clinical stroke for which hemorrhagic events were the most common causes." (PMID 41311701, 2025). "The most prevalent COL4A2 gene variants, identified through WES in all our stroke patients, include COL4A2 rs4238272 (c.297G > A), COL4A2 rs439831 (c.3804T > A), COL4A2 rs409858 (c.3807T > C), and COL4A2 rs438758 (c.4083T > C)." (PMID 41379817, 2025). "While COL4A1 and COL4A2 were common denominators for most of the stroke subtypes, high-density lipoprotein was inversely associated with small vessel stroke." (PMID 39268810, 2024). "As per previous strudies highlighting the pathogenicity of the COL4A2 p.Glu1123Gly variant, our research also identified four of the most prevalent COL4A2 gene variants in our stroke patients: COL4A2 rs4238272 (c.297G > A), rs439831 (c.3804T > A), rs409858 (c.3807T > C), and rs438758 (c.4083T > C)." (PMID 41379817, 2025). "A candidate gene-based meta-analysis of GWAS in a subtype of stroke patients and controls with European ancestry identified three common variants, rs9521732, rs9521733, and rs9515199, from the intronic regions of COL4A2 that were significantly associated with deep ICH." (PMID 36294301, 2022). "The presence of both rare and common risk variants in HTRA1 points to it being a key molecule in lacunar stroke pathogenesis, and is a feature shared with another gene identified in this study, COL4A2, in which rare variants also cause monogenic forms of cerebral small vessel disease." (PMID 33773637, 2021). "Moreover, COL4A2 was associated with ICHs and white matter hyperintensities in stroke patients and ‘community populations’, suggesting that susceptibility factors are shared between stroke patients and the general population." (PMID 29895609, 2018). "The Col4a2 variant of collagen type IV is associated with various phenotypes, including prenatal and neonatal intracranial hemorrhage, porencephaly, porencephaly with cataracts, focal cortical dysplasia, schizencephaly, strokes in childhood and adolescence, and sporadic delayed hemorrhagic stroke." (PMID 39006838, 2024). "Thus, stroke due to COL4A2 mutations might likely be more common in the population than currently appreciated." (PMID 24001601, 2014). "Genetic variants in COL4A1 and COL4A2 (encoding collagen IV alpha chain 1/2) occur in genetic and sporadic forms of cerebral small vessel disease (CSVD), a leading cause of stroke, dementia and intracerebral haemorrhage (ICH)." (PMID 39216230, 2024). "Multi-ethnic, genome-wide meta-analyses of dementia- and stroke-free subjects revealed that an SNP, rs9515201, at an intronic region of COL4A2 is associated with WMH in community populations, as well as stroke patients." (PMID 36294301, 2022). "Variants in COL4A1 and COL4A2 have been reported in patients diagnosed with CP41–44, however genetic testing was generally only performed upon evidence of recurrent stroke or evolution of multi-systemic clinical phenotypes." (PMID 34531397, 2021). "We identified potentially damaging point mutations in COL4A2, a gene associated with hemorrhagic stroke, in cases G and Q (OMIM 120090), thus contributing to the understanding of stroke in the etiology of hemiplegic CP." (PMID 28771244, 2018). "Furthermore, our study identified several novel and common gene variants in stroke patients through WES, including COL4A2, PSEN2, NOTCH3, and RNF2." (PMID 41379817, 2025). "Regarding genetic disorders that may cause strokes, COL4A1 mutation was mentioned in nine articles, while COL4A2 was mentioned in four articles." (PMID 38790247, 2024).
Stroke (continued). "These loci provide insights into lacunar stroke pathogenesis, highlighting disruption of the vascular extracellular matrix (COL4A2, LOX, SH3PXD2A, GPR126, HTRA1), pericyte differentiation (FOXF2, GPR126), TGF-β signalling (HTRA1), and myelination (ULK4, GPR126) in disease risk." (PMID 33773637, 2021). "However, one third of the genes were increased with suboptimal timing in aged rats, either on day 3 post-stroke (Adam17, Gpc3, Mmp14, Nid2, Tagln, Wnt5b) or on day 14 after stroke (Col4a2, Col8a1, Cthrc1, Cxcl1, Gpc3, Tgfbr2)." (PMID 23251410, 2012). "Cognitive features were the most common clinical cerebral phenotype for 4 of 7 genes (HTRA1HomZ, COL4A2, HTRA1HetZ, and CTSA); stroke was the most common among individuals with COL4A1 and ADA2, and headache was most common among individuals with TREX1." (PMID 35699195, 2022). "Clinical phenotype frequencies varied widely: stroke, 9% (TREX1) to 52% (HTRA1 heterozygotes); cognitive features, 0% (ADA2) to 64% (HTRA1 homozygotes); and psychiatric features, 0% (COL4A2; ADA2) to 57% (CTSA)." (PMID 35699195, 2022). "The frequency of clinical stroke ranged from 22% to 52% for 6 of 7 genes (COL4A2, 22% [9/41]; HTRA1HomZ, 30% [13/44]; ADA2, 33% [115/346]; COL4A1, 41% [161/390]; CTSA, 50% [7/14]; HTRA1HetZ, 52% [43/82]), while only 9% (11/123) of TREX1 individuals were reported to have suffered a clinical stroke." (PMID 35699195, 2022).
breast carcinoma (14 papers, 2015 to 2025). "It has been postulated that extracellular matrix-related COL4A2 is associated with breast cancer and may be a potential biomarker for early diagnosis and therapy of breast cancer." (PMID 27906681, 2017). "COL4A2 is widely expressed in different tumor tissues, and abnormally high COL4A2 expression has been found in cancers such as hepatocellular carcinoma, breast cancer and glioma." (PMID 39220121, 2024). "Breast cancer cells adapted to acidosis acquire resistance to anoikis by the increased production of fibrillar collagen, including COL4A2, therefore actively depositing extracellular matrix." (PMID 35159353, 2022). "A future challenge will be to determine the mechanisms of Col4A2 in regulating breast cancer incidence." (PMID 27906681, 2017). "A study carried out in breast cancer cell line MCF-7 showed that the reduction of COL4A2 mRNA level may lead to increased invasiveness of MCF-7 cells." (PMID 37592228, 2023). "COL4A2 is likely a potential biomarker in esophageal cancer, lung cancer, and breast cancer." (PMID 36120570, 2022). "COL4A2 was demonstrated to be involved in the tumorigenesis of the reproductive system organs, prostate cancer, epithelial ovarian cancer, uterine leiomyoma, breast cancer and etc.." (PMID 34681181, 2021). "A recent study performed in the breast cancer cell line MCF-7 revealed that the reduction of COL4A2 mRNA levels by miR-29b may contribute to the invasiveness of MCF-7 cells." (PMID 27906681, 2017). "It was also shown that COL4A2 is overexpressed in TNBC cells; therefore, it can be assumed that the COL4A2 protein plays an important role in the pathogenesis of this breast cancer subtype." (PMID 34681181, 2021). "This is in line with a previous study on breast cancer cells showing that C1QTNF6, SPARC, and COL4A2 were targeted by miR-29b." (PMID 29176935, 2017). "Of the two dbVar whole-gene DUPs, the COL4A2 339,611 bp CG, with breakpoints disrupting COL4A1 and NAXD, observed in a single African patient is defined as a PP-SV, as COL4A2 indicating oncogenic behaviour in gastric and breast cancers." (PMID 38947031, 2024). "The higher levels of circulating collagen IV in breast cancer patients with metastasis than in patients without metastasis illustrates the role of COL4A2 in the development of metastasis." (PMID 35159353, 2022).
hemorrhagic stroke (13 papers, 2014 to 2026). A stroke caused by a bleed on the brain. "Mutations in COL4A1 or COL4A2 were contribute to a broad spectrum of disorders, including glaucoma, myopathy, and hemorrhagic stroke." (PMID 31736743, 2019). "Collagen, type IV, alpha 2 (COL4A2) is an abundant component of BL of the cerebral vasculature and Col4a2 mutations cause small-vessel disease and hemorrhagic stroke." (PMID 24672479, 2014). "Additionally, SPS increased Col4a2 (collagen type IV alpha 2 chain) gene expression in IL, with mutations in Col4a2 being associated with hemorrhagic stroke." (PMID 39628496, 2024). "In contrast, COL4A2 variants often show slightly less severe cerebrovascular phenotypes, such as BSVD or adult‐onset hemorrhagic stroke, with lower penetrance." (PMID 41499643, 2026). "For instance, Pathogenic or Likely Pathogenic variants in G6PD predispose to kernicterus associated with neonatal jaundice, while COL4A2 and ABCC6 are associated with both ischemic and hemorrhagic stroke." (PMID 41282771, 2025). "This association is particularly interesting as rare mutations in COL4A2 and the closely related COL4A1 protein lead to small vessel disease and hemorrhagic stroke,28, –, 30 and common variants in close LD with this SNP (r2 > 0.8) have been linked to sporadic small vessel disease." (PMID 26674333, 2016). "However, further understanding of retinal vascular pathology could be useful in developing therapeutics to prevent hemorrhagic strokes in patients with COL4A1 and COL4A2 mutations." (PMID 26813606, 2016). "Together, these findings suggested that patients with COL4A1 and COL4A2 mutations may be at a higher risk of retinal hemorrhages, and retinal examinations may be useful for identifying patients with COL4A1 and COL4A2 mutations who may also be at a higher risk of hemorrhagic strokes." (PMID 31484286, 2019). "Together, our findings suggest that patients with COL4A1 and COL4A2 mutations may be at elevated risk of retinal hemorrhages and that retinal examinations may be useful for identifying patients with COL4A1 and COL4A2 mutations who are also at elevated risk of hemorrhagic strokes." (PMID 26813606, 2016). "Moreover, the reduced penetrance implies that in the absence of an extensive family history, familial haemorrhagic stroke caused by COL4A2 mutations might be mistakenly classified as sporadic." (PMID 24001601, 2014).
intracerebral hemorrhage (13 papers, 2016 to 2025). A cerebrovascular disorder characterized by bleeding into one or both cerebral hemispheres including the basal ganglia and the cerebral cortex. "Common genetic variants in COL4A1 and COL4A2 have been associated with intracerebral haemorrhage (ICH) in the general population while rare mutations, mostly affecting glycine resides, cause the hereditary COL4A1 syndrome." (PMID 33745160, 2021). "COL4A1/COL4A2 mutations cause a multi-systemic disorder encompassing cerebrovascular disease, including intracerebral haemorrhage (ICH), as well as eye and renal defects including HANAC syndrome." (PMID 30351356, 2019). "Patients with single-allele mutations of COL4A2 suffer from autosomal dominant porencephaly type 2, cerebral small vessel disease, recurrent intracerebral haemorrhages (ICH), hydrocephalus, schizencephaly or severe eye defects." (PMID 31331924, 2019). "Mutations in the collagen genes COL4A1 and COL4A2 cause Mendelian eye, kidney and cerebrovascular disease including intracerebral haemorrhage (ICH), and common collagen IV variants are a risk factor for sporadic ICH." (PMID 30351356, 2019). "Similarly, mutations in COL4A2 have been associated with porencephaly, intracerebral haemorrhages, optic atrophy, and ONH." (PMID 32040484, 2020). "In addition to prenatal and perinatal hemorrhages, COL4A1 and COL4A2 mutations also caused the sporadic and recurrent intracerebral hemorrhages (ICH) in young and old patients." (PMID 31484286, 2019). "Mutations in COL4A1 and COL4A2 cause highly penetrant cSVD as part of the multisystem disorder known as Gould syndrome, which includes cerebrovascular manifestations such as porencephaly, early-onset stroke, leukoencephalopathy, and intracerebral hemorrhage (ICH)." (PMID 41311701, 2025). "Col4a1 and Col4a2 mutant mice model mirror several types of human disease such as anterior segment ocular dysgenesis, glomerulopathy and spontaneous intracerebral hemorrhage." (PMID 33918807, 2021). "Furthermore, missense mutations in COL4A1/COL4A2 caused rare familial forms of cerebral SVD, manifesting as deep intracerebral hemorrhages, lacunar ischemic strokes, and WMHs." (PMID 31484286, 2019).
liver fibrosis (13 papers, 2017 to 2025). "Multitranscriptome study indicated that COL4A2 is a gene specifically associated with liver fibrosis and that it positively correlates with the development of hepatic fibrosis." (PMID 37266443, 2023). "Col4a2 and Pdgfr-β are liver-fibrosis-specific genes associated with the PI3K/AKT signaling pathway, and their expression levels are intimately tied to the severity of liver fibrosis." (PMID 40243656, 2025). "Notably, COL4A2 and LAMC1 were closely associated with ECM-receptor interactions, suggesting that Lira mitigates liver fibrosis by inhibiting these pathways." (PMID 41377138, 2025). "Classical fibrotic mediators and markers (including Tgfb1, Timp1, and Vcam1), collagen of the ECM (including Col4a1, Col4a2, Col16A1, and Col18a1) and cell surface adhesion and signaling integrin (Itga2, Itga5) were found to be differentially expressed in the enriched hepatic fibrosis pathways." (PMID 39747668, 2025). "Notably, Lira significantly regulated ECM-receptor interactions, particularly by decreasing LAMC1 and COL4A2 protein levels, suggesting a potential mechanism for ameliorating hepatic fibrosis." (PMID 41377138, 2025). "Among the genes, further analysis disclosed that the gene expression levels of TLR2, Col1a1, Col1a2, Col4a1, Col4a2, and Pdgfr-β were changed during the SCU anti-liver-fibrosis process, and qRT-PCR verified this result." (PMID 40243656, 2025). "On the basis of transcriptomics and network pharmacology findings, genes connected with liver fibrosis and the PI3K/AKT signaling pathway, such as Col1a1, Col1a2, Col4a1, Col4a2, TLR2, and Pdgfr-β, were chosen for qRT-PCR validation." (PMID 40243656, 2025). "The significant enrichment of hepatic fibrosis/hepatic stellate cell activation (z = 0, p < 1e-5) largely due to the downregulation of several collagens (COL1A1, COL4A1, and COL4A2) was present in cluster 4 that contained nearly all control iAstros." (PMID 36590162, 2023). "We found that COL1A1, COL4A2, and α-SMA mRNA expressions were significantly increased in the liver of the model, while the transcription of such liver fibrosis-related genes was significantly inhibited by GFL." (PMID 36278176, 2022). "Given that COL4A1 and COL4A2 were among the most upregulated collagens in human cirrhotic livers, we hypothesized that COL4 is regulated by TNF-α and has a role in liver fibrosis and PHTN." (PMID 38713515, 2024). "In a recent multi-transcriptome analysis, COL4A2 and LAMB1 were identified as prioritized genes specifically associated with liver fibrosis progression, independent of etiology." (PMID 39585303, 2024).